IL10 (interleukin 10)
Diseases named in the same sentence as IL10 in open-access papers (continued):
Sharing a sentence is not in itself a finding about the gene and the disease.
Hypertension (continued). "IL-10 is an anti-inflammatory factor secreted by Tregs and plays an important cardiovascular protective role in hypertension, while IL-17A is a proinflammatory factor secreted by Th17 cells that contributes to the maintenance of elevated blood pressure." (PMID 35502169, 2022). "Circulating IL-10 levels were significantly decreased in essential hypertensive patients compared to normotensive subjects." (PMID 35528508, 2022). "Numerous studies have indicated that IL-10 is a potent vascular cytokine and has been shown to reduce hypertension and inflammation-mediated senescence of the vasculature." (PMID 34101754, 2021). "IL-10 is an anti-inflammatory cytokine exhibiting a protective effect on vascular dysfunction in hypertension." (PMID 33532132, 2021). "These and other data suggest that Treg-derived IL-10 mediates the beneficial effects of Tregs in hypertension." (PMID 33394136, 2021). "Experiments showed that the expression of IL-1β in the PVN region of spontaneously hypertensive rats was elevated, and the expression of anti-inflammatory cytokine IL-10 decreased, indicating that hypertension is accompanied by inflammation." (PMID 33746706, 2021). "Single-factor logistic regression analysis showed that BMI, a history of hypertension, FPG, HbA1c, and the serum TC, IL-6, and IL-10 concentrations were risk factors; whereas, the serum Zn and Mg concentrations and eGFR were protective." (PMID 33859989, 2021). "Treg cells from rats with mild hypertension produced more IL-10 than did those from salt-sensitive rats." (PMID 33083327, 2020). "The levels of TNF-α, IL-2, IL-6 and IL-10 in serum were determined in mercury-exposed participants, suffering from hypertension." (PMID 33083327, 2020). "Elevated levels of IL-1β, IL-10, and TNF-α are also correlated with increased arterial stiffness associated with hypertension." (PMID 33265898, 2020). "Prolonged mercury exposure increases the risk of developing hypertension through systemic inflammation, as demonstrated by elevated levels of serum inflammatory cytokines TNF-α, IL-2, IL-6 and anti-inflammatory cytokine IL-10." (PMID 33083327, 2020). "Treg cells prevent hypertension via the inhibition of innate and adaptive immune responses, and these cells reduce blood pressure by releasing IL-10." (PMID 32724324, 2020). "In general, IL-10 improves vascular and renal functions in hypertension, although little has been reported on the effects of this cytokine on hypertension, particularly in immune environments that favor the development of fibrosis." (PMID 31360120, 2019). "While the pro-inflammatory cytokines such as IL-17, IFN-γ, and TNF-α have a detrimental effect in the pathogenesis of hypertension, the role of anti-inflammatory IL-10 is protective." (PMID 31321561, 2019). "VD possesses the potential of serving as a safe and effective adjuvant to oral nifedipine in treating women with preeclampsia against hypertension, possibly through the upregulation of IL-10 and the downregulation of TNF-α." (PMID 29225576, 2017). "AngII induced hypertension was reduced in ICV etanercept infused mice, with reduced pro-inflammatory cytokine expression and increased IL-10 levels, providing intriguing evidence for the role of the neurohormonal/inflammatory axis in hypertension." (PMID 26121471, 2015). "Collectively, these results suggest that IL-10 generated by the immunosuppressive Treg cells protects against Ang II-induced vascular dysfunction and hypertension development by suppressing oxidative stress." (PMID 25387998, 2014). "Many studies have found that IL-10 is a key mediator of vascular protection in atherosclerosis, type II diabetes and hypertension." (PMID 25387998, 2014). "In our studies, pregnant IL-10−/− mice exhibit mild hypertension, endothelial dysfunction, and proteinuria only during pregnancy." (PMID 24904596, 2014).
Hypertension (continued). "In a previous work, enalapril (another ACE inhibitor) was able to produce an increase in plasma levels of IL-10 in patients with coronary artery disease and arterial hypertension." (PMID 20462420, 2010). "In contrast, a decrease in plasma levels of IL-10 has been found in patients with coronary artery disease and arterial hypertension, and in patients with pulmonary arterial hypertension." (PMID 20462420, 2010). "Conventional risk factors were more frequent among patients with IL-10 concentrations above median, including elevation of CRP and IL-6 but excluding previous MI and hypertension." (PMID 17690160, 2008). "The anti-inflammatory factor IL-10, produced by Tregs, can effectively improve hypertension." (PMID 37465757, 2023). "To explore whether IL-10 is involved in hypertension-related vascular remodelling, we first measured the plasma IL-10 levels in normal blood pressure subjects and patients with untreated hypertension." (PMID 35528508, 2022). "Th1 and Th17 cells release pro-inflammatory cytokines, such as IFN-γ, TNF-α, and IL-17a, which are prominent pathogens in hypertension models while Treg cell inhibits Ang II-induced hypertension by releasing anti-inflammatory cytokines, which mainly include IL-10 and TGF-β." (PMID 36457803, 2022). "Furthermore, the inflammation is characterized by increased levels of local inflammatory cytokines such as TNF, IL10, and PTGS2, which are more likely to be useful diagnostic tools for hypertension in the future." (PMID 35308213, 2022). "Taken together, a regulatory relationship between intestinal microbiota and IL-10 could be established which show beneficial influences on hypertension, suggesting that diversity of intestinal flora may ameliorate healthy state." (PMID 36195874, 2022). "Moreover, pregnant interleukin-4 (IL-4 -/-) exhibit mild preeclampsia-like symptoms, and interleukin-10 (IL-10 -/-) knockout mice exposed to hypoxia present placental injury, proteinuria, and hypertension." (PMID 35493783, 2022). "Although the biological function has not been defined, IL-17 also seems to play a role in the process of IL-10 regulated hypertension, because IL-10 could suppressed the generation of Th17 cells while enhance the number of regulatory T cells." (PMID 36195874, 2022). "IL-10 was unable to alter blood pressure in the case of Ang II-induced hypertension." (PMID 35528508, 2022). "In addition, inhibition of microglial activation (reduced production of pro-inflammatory cytokines) or overexpression of IL-10 (an anti-inflammatory cytokine) in PVN through viral transfection attenuates Ang II-induced hypertension." (PMID 33967677, 2021). "Data showed that the use of Linalool for sub-chronic treatment could reduce the development of hypertension in SHRs, reduce cardiac hypertrophy, increase IL-10 anti-inflammatory cytokine, and improve vasodilatory function and decreasing vasoconstriction." (PMID 34627325, 2021). "We found an increase IL-10 in the serum of mercury-exposed residents with hypertension." (PMID 33083327, 2020). "However, SR rats are protected from hypertension following high-fructose intake by producing a large amount of anti-inflammatory cytokine IL-10, which is secreted by Treg lymphocytes." (PMID 32179549, 2020). "The participation of the proinflammatory state in the onset of hypertension is also illustrated by the attenuation of hypertension after reducing the inflammation status with intracerebroventricular infusion or oral delivery of minocycline or with the overexpression of IL-10 in the PVN." (PMID 31737062, 2019). "Sera from preeclamptic patients induce hypertension and proteinuria in pregnant interleukin 10 (IL-10) knockout mice, suggesting that factors in blood, including soluble endoglin (sENG) and soluble fms-like tyrosine kinase (sFlt1), induce preeclampsia-like features in mice." (PMID 31083536, 2019).
Hypertension (continued). "Thus, the aim of this work was to determine the Th1/Th17 (IL-6, IL-2, TNF, IL-17 and IFN-γ) and Th2 (IL-4 and IL-10) serum profile in Venezuelan Chagasic patients stratified according amiodarone treatment, hypertension and arrhythmias." (PMID 28327099, 2017). "In the present study, increased IL-10 levels in hypertension disorders, i.e., EC in pregnant women might be due to protective responses against inflammation." (PMID 28348564, 2017). "In contrast, IL-10 plays a protective role against hypertension." (PMID 26783414, 2016). "In contrast, IL-10 in the PVN plays a protective role against hypertension and heart failure." (PMID 25885968, 2015). "Indeed, OSA patients with hypertension show reduced values of IL-10 accompanied by increased levels of TNF-α, IL-6, and CRP with respect to patients without high blood pressure." (PMID 25944984, 2015). "More importantly, inhibition of TLR4 by bilateral microinjection into the PVN of the SHR rats delays the progression of hypertension; reduces cardiac hypertrophy; attenuates PICs, iNOS, and NFκB, as well as NE levels; and improves anti-inflammatory IL-10 levels within the PVN." (PMID 25879545, 2015). "IL-6 and IL-10 levels were slightly increased in T2DM patients with hypertension." (PMID 23762057, 2013). "Expression of IL-6, a cytokine implicated in vascular disease and hypertension, was not altered in old wild-type, but was increased substantially in old IL-10 knockout mice." (PMID 24400151, 2013). "Taken together, these findings suggest that endogenous IL-10 could be a therapeutic target to reduce ischemic damage especially under hypertension." (PMID 24499655, 2013). "Recent discoveries indicate that besides elevated levels of circulating and brain PICs, anti-inflammatory cytokines (AICs) such as IL-10 have a significant impact on sympathetic outflow, arterial pressure and cardiac remodeling in experimental models of hypertension." (PMID 23285093, 2012). "In the same way, it could be suggested that IL-10 might be a mediator of cardiac protection against arterial hypertension." (PMID 20462420, 2010). "Assuming that inflammation may be the underlying mechanism in the relationship between MASLD and hypertension, we evaluated cytokines (TNF-α, IL-6, IL-10, IL-4, and IL-13) in the liver of patients with morbid obesity, MASLD, and SAH compared to patients without SAH." (PMID 39337863, 2024). "Therefore, we hypothesize that the vascular remodelling process induced by hypertension can be ameliorated by recombinant IL-10 protein administration." (PMID 35528508, 2022). "Furthermore, the pro-inflammatory cytokine IL-17, released in part by Th17, induces ROS-mediated endothelial dysfunction, whereas anti-inflammatory cytokine IL-10, produced by Tregs, is shown to protect endothelial function in hypertension by attenuates NADPH oxidase activity." (PMID 34578849, 2021). "IL-10 may inhibit angiotensin via the NF-κB pathway, thereby inhibiting fibroblast proliferation and collagen synthesis and eventually inhibiting myocardial interstitial fibrosis, indicating that IL-10 may be able to prevent and alleviate hypertension LVH." (PMID 33879070, 2021). "Similarly, IL-10 levels gradually increased from mild to severe hypertension disorder groups." (PMID 28348564, 2017). "In addition, IL-10 overexpression in the PVN attenuates Ang II-induced hypertension." (PMID 23691105, 2013). "Moreover, IL-10 also regulates the vascular remodeling and hypertension to maintain pregnancy." (PMID 23028860, 2012). "The downregulation of IL-10 and upregulation of TNF-α and IL-1β show a sustained inflammatory state, which is consistent with hypertension-driven low-grade inflammation as well as increased production of trimethylamine N-oxide (TMAO) in hypertensive models." (PMID 41515269, 2026). "The average level of CD14+IL-10+ cells consistently differed between the groups: control—0.77; IQR 1.09, hypertension—68.65; IQR 7.52 and preeclampsia—55.68; IQR 31.02." (PMID 41463130, 2025).
Hypertension (continued). "In our OSA patients with concomitant arterial hypertension, there were increased concentrations of CCL3 and IL-10." (PMID 36769452, 2023). "We hypothesize that the inclusion of only women with preeclampsia confirmed by proteinuria and hypertension, as well as the exclusion of patients with fetal growth restriction and fetal distress from the study group, may have contributed to the elevated levels of IL-10." (PMID 37168313, 2023). "From these cytokines, IL-1β, TNF, IL-29, IFN-α2, IL-28, GM-CSF, IFN-β, IL-10 and IFN-γ exhibited increased level in patients with hypertension in the second outbreak in comparison to those from the first one." (PMID 36817433, 2023). "Jiaodavirus was positively correlated with proinflammatory activity (IL-18, IL-10, MCP-1), IR (HOMA-IR and insulin levels), and hypertension (DBP percentile)." (PMID 37342535, 2023). "IL-6 (p = 0.035), IL-8 (p <0.0001), IL-10 (p = 0.009), and TNF-α (p <0.0001) serum levels were significantly higher in patients with arterial hypertension." (PMID 37969879, 2023). "The proinflammatory profile during ANGII-induced hypertension is accompanied by a destabilized and reduced antiinflammatory CD4+FoxP3+ Treg response along with a decrease in IL-10 production." (PMID 35133978, 2022). "In the PPI network, a total of 14 targets, such as TNF, CHRM1, ACE, IL10, PTGS2, REN, and F2, were the hub targets of MVO for treating hypertension." (PMID 35308213, 2022). "Expression of IL-10, IL-8, IL-1β, IL-6, IL-4, TGFβ1, TNFα and GM-CSF significantly decreased in the CSWT group compared with the hypertension group." (PMID 36362064, 2022). "Hypertension may induce liver regeneration and fibrosis through an endothelial dysfunction due to increased angiocrine signals and may also be triggered by glucose intolerance and decreased interleukin-10-mediated or heme oxygenase-1-induced anti-inflammatory mechanisms." (PMID 35268536, 2022). "In the past few years, important roles of at least 5 cytokines have been identified in hypertension, including IL-17, interferon γ (IFN-γ), TNF-α, IL-6, and IL-10." (PMID 35528508, 2022). "Spontaneous hypertension also increased myocardial TNF-α, IFN-γ, and pro-fibrotic IL4, but decreased myocardial IL6 and IL10." (PMID 34368120, 2021). "In this study, the expression of CD163 and CD206 in peripheral blood monocytes and the concentrations of IL-10 and TNF-α in the serum of patients with hypertension and healthy participants were detected." (PMID 33879070, 2021). "Mercury-exposed citizens, especially those with hypertension, had significantly higher concentrations of inflammatory cytokines TNF-α, IL-2, IL-6 and anti-inflammatory cytokine IL-10 as compared to the unexposed population." (PMID 33083327, 2020). "Increased secretion of IL-10 and TGF-β had a protective effect on hypertension and regulated the endothelial function, dilated the blood vessels, and reduced proteinuria and renal injury in patients with hypertension." (PMID 32724324, 2020). "Hypertensive patients have higher circulating levels of the inflammatory cytokines IL-1β, IL-10, and tumor necrosis factor-alpha (TNF-α), indicating the potential use of these inflammatory biomarkers as markers for hypertension." (PMID 33265898, 2020). "In addition, increased function of Tregs decreases the expression of Ang II and improves aldosterone-induced hypertension, cardiac fibrosis, coronary inflammation, electric remodeling and endothelial-dependent vasodilation, which are likely partly mediated by the release of IL-10 from Tregs." (PMID 31196042, 2019). "In Wistar rats, IL-10 is upregulated in viable neurons in the ischemic brain following permanent and transient MCAO, and hypertension blunts this response, potentially contributing to the worse outcomes in the hypertensive setting." (PMID 28659854, 2017). "In the hypertension disorders group, significantly SBP is negatively correlated with IL-6 (r = 0.447, p < 0.0133) and IL-10 (0.556, p < 0.0048)." (PMID 28348564, 2017).
Hypertension (continued). "Serum from PE patients induces the clinical features of PE such as hypertension, proteinuria, and FGR in IL-10−/− mice." (PMID 24904596, 2014). "It demonstrated better survival rates, minimal endothelial damage, no hypertension, and reduced vascular inflammation via IL-10." (PMID 40431578, 2025). "For hypertension or CVD, TNFR1 mediated 74.2% of the positive association with IL-10 independent of IL-6, while IL-6 mediated 47.9% of the association independent of TNFR1." (PMID 41280118, 2025). "Key vascular effects of polymerized hemoglobin exposure included the absence of hypertension, minimal endothelial damage with slight alterations in iNOS, and a reduction in vascular inflammation mediated by IL-10." (PMID 40431578, 2025). "Conversely, when patients with renal disease and hypertension were treated with valsartan at a daily dose of 100 mg for 1 week, there were no significant changes in IL‐10 levels." (PMID 38504425, 2024). "Moderate positive correlations of the T2 with IL-7 (ρ = 0.455; p = 0.033), IL-10 (ρ = 0.578; p = 0.005), IL-12P40 (ρ = 0.500; p = 0.018), and IL-17A (ρ = 0.452; p = 0.035) levels were observed only in patients without hypertension." (PMID 39685774, 2024). "Furthermore, it has been shown that IL-10 deletion in a murine heart failure model attenuates erroneous fibrotic response and reduces mortality, suggesting IL-10 signaling cascades may be relevant therapeutic targets to prevent the progression of hypertension into heart failure." (PMID 36970367, 2023). "Magnesium acts as an allosteric activator for adenylate cyclase, Na/K-ATPase, and phospholipase C. Magnesium downregulates IL-1 alpha, IL-4, IL-6, IL-1 beta, Il-10, IL-12, TNF-alpha and several chemokines involved in hypertension, numerous immune-inflammatory pathways, and in adverse pregnancies." (PMID 38807919, 2022). "Moreover, DEL-1–Fc injections during hypertension resulted in higher numbers of CD25+FoxP3+ Tregs and increased IL-10 compared with injections of DEL-1–RGE–Fc." (PMID 35133978, 2022). "In conclusion, we demonstrated that IL-10 treatment reverses vascular structural alterations in hypertension without normalizing blood pressure." (PMID 35528508, 2022). "Irbesartan also increased the expression of IL-10 and inhibited the expression of TNF-α in the culture supernatants of monocyte from hypertensive patients with LVH in a concentration-dependent manner; of these groups, the 10−6 mol/L group exhibited the most significant differences (P < 0.01)." (PMID 33879070, 2021). "Irbesartan also increased the expression of IL-10 and inhibited the expression of TNF-α in the culture supernatants of monocytes from hypertensive patients with LVH in a concentration-dependent manner; of these groups, the 10–6 mol/L group exhibited the most significant changes." (PMID 33879070, 2021). "In Ang II–dependent hypertension, there is an imbalance between Th17/Treg in the spleen and in renal/cardiac infiltrating lymphocytes resulting in increased expressions of IL-17A, IL-23, and TNF-α, and decreased expression of IL-10." (PMID 31321561, 2019). "We demonstrated that hypertension exacerbated Pb-induced neuroinflammation in the prefrontal cortex (PFC), hippocampus, and hypothalamus, as evidenced by increased levels of proinflammatory cytokines (IL-6 and TNF-α) and decreased levels of anti-inflammatory cytokines (CD206 and IL-10)." (PMID 39853035, 2025). "Similarly to age, TNFR1, IL-6, and TNF-a collectively mediated 100% of the positive association between hypertension or CVD and IL-10, although none were significant independently." (PMID 41280118, 2025). "Notably, there was no compensatory increase in the anti-inflammatory cytokine IL-10 at any time point, suggesting that protective regulatory countermeasures were not deployed prior to or during the development of hypertension in this model." (PMID 39361560, 2024).